CIMAP2 (ciliary microtubule associated protein 2)
Synonyms: LEM; LEXM; C1orf177; FLJ40201
Tractability: No criterion of Open Targets' tractability assessment is met for any kind of drug.
Gene: Protein-coding gene on chromosome 1 (54,806,063 to 54,842,252, forward strand). Ensembl gene ENSG00000162398.
Genetic constraint (gnomAD): Loss-of-function variants: 48 observed, 51.06 expected, observed/expected ratio (o/e) 0.94, 90% interval 0.75 to 1.2. The upper end of that interval is the gene's LOEUF score, 1.2, which puts it in group 5 of 6, group 1 being the genes least tolerant of losing a copy. Missense variants: 524 observed, 529.88 expected, observed/expected ratio (o/e) 0.99, 90% interval 0.92 to 1.06. Synonymous variants: 189 observed, 196.15 expected, observed/expected ratio (o/e) 0.96, 90% interval 0.86 to 1.09.
Homologues: Orthologues: chimpanzee CIMAP2 (98% identical), macaque CIMAP2 (95% identical), pig CIMAP2 (75% identical), dog CIMAP2 (74% identical), guinea pig CIMAP2 (73% identical), rabbit CIMAP2 (72% identical), rat Cimap2 (71% identical), mouse Cimap2 (69% identical).
Diseases named in the same sentence as CIMAP2 in open-access papers:
CIMAP2 is named in the same sentence as 5 diseases in open-access papers, as found by Europe PMC text mining. Sharing a sentence is not in itself a finding about the gene and the disease.
CIMAP2 shares sentences with these, for which no sentence is quoted: cancer (1 paper); cervical adenocarcinoma (1); cervical cancer (1); cervical squamous cell carcinoma (1); tumor (1).